WT1 (WT1 transcription factor)
Diseases named in the same sentence as WT1 in open-access papers (continued):
Sharing a sentence is not in itself a finding about the gene and the disease.
Primary amenorrhea (1 paper, 2010). "We directly sequenced SRY, SF1 and WT1 genes in 15 adolescent girls with primary amenorrhea, low testosterone concentration, and XY karyotype, to determine the prevalence of mutations." (PMID 20302644, 2010). "We specifically focused on SRY, SF1 and WT1 because these genes have previously been reported to be implicated in adolescents presenting with primary amenorrhea due to 46,XY DSD in association with low pl-T, but no other signs." (PMID 20302644, 2010). "To conclude, the genetic analysis of low-testosterone primary amenorrhea due to 46,XY DSD is complex since several factors may be involved, including SRY, SF1, WT1 and LH receptor." (PMID 20302644, 2010).
pseudomyxoma peritonei (1 paper, 2023). An appendix cancer that is characterized by progressive accumulation of mucus-secreting tumor cells within the abdomen and pelvis. "AGN343 patient had a pseudomyxoma peritonei (CK7 − /CK20 score 3 + /CDX2 score 3/SABT2 score 1, and ER − /PAX8 − /WT1 −); she underwent right and transversal colectomy during debulking, but neither primary cancers nor polyps were identified." (PMID 36346458, 2023).
serous neoplasm (1 paper, 2025). "In contrast, expression of WT1 (Wilms Tumour 1), a characteristic marker of serous neoplasms, was lost in HGSC_3 organoids." (PMID 40835947, 2025).
small cell carcinoma (1 paper, 2013). A neuroendocrine carcinoma composed of small malignant cells which are often said to resemble "oat cells" under the microscope. "Although SCCOHT is morphologically similar to small cell carcinomas from other sites, its common expression of WT1 and lack of thyroid transcription factor (TTF)-1 allows it to be distinguished from other small cell cancers." (PMID 23433318, 2013).
small intestinal cancer (1 paper, 2024). "We report a case in which a combination of WT1-DC and α-Galcer-DC was effective in shrinking cancer in a patient with small intestinal cancer who had been diagnosed with a life expectancy of three months after failure of chemotherapy." (PMID 39035592, 2024). "We report a case in which radiotherapy, WT1-DC, and α-Galcer-DC were effective as a combination in a terminal small intestinal cancer with a life expectancy of two months, in which chemotherapy was ineffective." (PMID 39035592, 2024).
solitary fibrous tumor (1 paper, 2021). Solitary fibrous tumor (SFT) represents a diverse group of ubiquitous rare spindle cell neoplasms that may be benign or malignant and that most frequently arises from the pleura and peritoneum and rarely from other sites such as head and neck, liver and skeletal muscle. "However, the immunoreactivity for STAT-6, along with a concomitant negativity for WT1, favors the diagnosis of solitary fibrous tumor." (PMID 33445443, 2021).
steatosis (1 paper, 2022). Increased lipid within the cytoplasm of cells. "Accordingly, wild-type mice showed severe hepatic steatosis with clearly milder changes in the Wt1 heterozygotes." (PMID 34846543, 2022).
T-cell leukemia (1 paper, 2024). A malignant disease of the T-lymphocytes in the bone marrow, thymus, and/or blood. "Similar observation has been reported in an earlier study suggesting that loss of function in WT1 gene may cooperate in disease pathogenicity of T-cell leukemia." (PMID 38459434, 2024).
trisomy (1 paper, 2023). A chromosomal abnormality consisting of the presence of one chromosome in addition to the normal diploid number. "The most frequent co-occurring somatic aberrations were by far WT1 mutations, FLT3-ITD (high ratios being associated with increased WBC count and BM blast infiltration) and trisomy 8 (85% of cases carried at least one of these aberrations and 47% had at least two)." (PMID 37085611, 2023).
trisomy 8 (1 paper, 2022). "It is usually associated with other chromosomal abnormalities, particularly trisomy 8, and other genetic mutations, such as FLT3-ITD, WT1, and CEBPA, and appears to play a role in histone methylation and acetylation." (PMID 35740427, 2022).
urinary tract obstruction (1 paper, 2021). Blockage of the normal flow of contents of the urinary tract. "Without evidence of urinary tract obstruction, we further examined HNF1B, HNF4A and WT1 immunostainings on serial embryonic sections, focusing on glomeruli with different degrees of Bowman's capsule expansion." (PMID 33737325, 2021).
uterine sarcomas (1 paper, 2025). "WT1 has been recognized as an independent negative prognostic marker for overall survival, highlighting its biological and clinical significance in uterine sarcomas." (PMID 40725576, 2025).
virus infection (1 paper, 2020). "Cell membrane permeability changes caused by Wt1-5 infection can also suggest a relationship between virus infection and apoptotic cell death, as apoptosis has been related with a series of physical changes occurring in the cell membrane which include the increase in permeability to some dyes." (PMID 32722005, 2020). "The expression of cell surface receptors used by Wt1-5 was determined using flow cytometry and an antibody blocking assay to test for their implication in virus infection." (PMID 32722005, 2020). "The ability of Wt1-5 infection to induce the expression of caspases 3 and 8 and pro-apoptotic proteins BAX, Bcl2, and BID suggest that virus infection, at least at late stages of the viral life cycle, leads to apoptotic cell death." (PMID 32722005, 2020).
Zinc deficiency (1 paper, 2025). A deficiency of the essential metal Zinc; an essential cofactor for many enzymes. "In this study, we assessed the mRNA expression levels of specific markers for podocytes, podocalyxin, WT1, and nephrin, to investigate changes in podocyte function under conditions of zinc deficiency." (PMID 39028478, 2025). "Our results indicate that zinc deficiency reduces specific markers of podocytes (podocalyxin, WT1, and nephrin) and activates the Wnt3a/β-catenin pathway, a key pathway in podocyte injury." (PMID 39028478, 2025).
tumor (823 papers, 1993 to 2026). "By linking SPI pharmacology to WT1-associated microenvironmental features and tumor suppression, our findings provide a mechanistic rationale for repurposing Spironolactone as an immunomodulator to overcome therapeutic resistance in genitourinary oncology." (PMID 41868121, 2026). "Mutations in the WT1 gene cause conformational changes in the binding capacity of the WT1 protein, leading to a deficient tumor-suppressing activity and creating a pro-tumor environment." (PMID 41102401, 2026). "The association between WT1 positivity and advanced tumor stage suggests a potential prognostic role." (PMID 41930078, 2026). "By contrast, in tumours with either somatic WT1 mutations or in mosaic chromosome 11p LOH, the driver landscape was less restrained." (PMID 39665570, 2025). "Wilms’ tumor gene 1 (WT1), found on chromosome 11p13, was initially identified as a tumor suppressor gene implicated in Wilms’ tumor but has since been recognized for its role in leukemogenesis." (PMID 40227798, 2025). "We did, however, find that the global pattern of methylation strikingly segregated one group of tumours, almost exclusively composed of cases harbouring WT1 (germline or somatic) and co-mutation of Wnt signalling genes." (PMID 39665570, 2025). "In support of this concept, PM frequently expresses immunogenic tumor-associated antigens, such as mesothelin and Wilms tumor 1 (WT-1), both capable of eliciting specific immune responses." (PMID 41463268, 2025). "To validate the seemingly preordained driver landscape of tumours in WT1 and TRIM28 predisposition, we searched for additional cases amongst children with bilateral tumours and/or a family history of Wilms." (PMID 39665570, 2025). "While WT1 at 11p13 (a specific location on the short arm (p arm) of chromosome 11, specifically band 13) was the first identified gene associated with the tumor, it is mutated in only a subset of cases (around 20%)." (PMID 40722750, 2025). "Four primary cell populations were first identified using canonical cell markers: WT tumor cells (WT1, NCAM1, SIX1, SIX2, PAX2), cancer-associated fibroblasts (CAFs) (ACTA2, TAGLN, COL1A1, PDGFRB), endothelial cells (PECAM1, CLDN5, ENG, VWF) and immune cells." (PMID 40098972, 2025). "Consistent with our previous findings, each tumour exhibited a second mutation in the underlying predisposition gene and in cases of WT1 predisposition, driver variants in Wnt signalling genes." (PMID 39665570, 2025). "In cancers such as breast cancer, non-small cell lung cancer, and Kaposi’s sarcoma, aberrant WT1 expression has been linked to chromatin remodeling, immune evasion, and altered tumor microenvironment dynamics." (PMID 40507300, 2025). "The Wilms'tumor 1 (WT1) gene encodes a tumor suppressor gene identified initially by its inactivation in the Wilms tumor, a pediatric kidney cancer." (PMID 40613901, 2025). "For example, we established a link between the upstream regulator WT1, encoded by a candidate EC GWAS susceptibility gene, and gene expression changes associated with tumour cell migration in GZD824‐treated Ishikawa cells." (PMID 39739675, 2025). "This type of neoplasia is common in children and linked to mutations in the Wilms' tumor suppressor gene (WT1)." (PMID 41451336, 2025). "Wilms tumor 1 (WT1) is a tumor-associated antigen expressed in solid tumors and hematological malignancies." (PMID 40847198, 2025). "Secondly, also in other WTs, the rhabdomyoblast/tumor mass ratio after chemotherapy and the presence of (WT1 mutation‐associated) muscle differentiation seemed to be associated with better prognosis." (PMID 40439002, 2025). "WGS data were available for 31 cases (46 tumor, 41 control samples), and targeted Sanger sequencing was performed on 30 WT samples (22 stromal-type, 8 epithelial-type) suspected of WT1 or TRIM28 mutations." (PMID 40340749, 2025).
tumor (continued). "The median age of diagnosis segregated by predisposition, with classical predisposition variants (e.g. in WT1 or TRIM28) generating tumours at a younger age than in the control group (10 vs. 36 months)." (PMID 39665570, 2025). "Instead, these effectors are restricted to conventional anti-tumor cytotoxicity via targeting tumor-associated antigens, such as MAGE or WT1, or tumor neoantigens, which are scarce in myeloid malignancies given their low relative mutational burden." (PMID 40558262, 2025). "WT1 has been found to be an important regulator of normal and malignant hematopoiesis, which is usually inactivated in APL patients and results in the complete loss of WT1’s inhibitory function on APL tumor cells." (PMID 38322990, 2024). "The Wilms’ Tumor 1 (WT1) gene serves primarily as a tumor suppressor, with its encoded protein playing a crucial role in the regulation of cellular processes such as proliferation, differentiation, and apoptosis." (PMID 39840278, 2024). "During the administration of the WT1 peptide vaccine, the maintenance of WT1 expression in tumor cells is significantly associated with a longer progression free and overall survival." (PMID 39555054, 2024). "Analysis of KS tumor specimens using immunohistochemistry also revealed that there is an important microenvironmental impact associated with WT1 expression." (PMID 38190392, 2024). "The early administration of the WT1 peptide vaccine after tumor collapse is expected to cause rapid clonal expansion of WT1-specific CTLs, which can attack WT1-expressing tumors and lead to a favorable clinical response." (PMID 39509060, 2024). "While tumor-associated antigens such as Wilms’ tumor 1 (WT1) protein, heat shock proteins (HSPs) and survivin are overexpressed by tumor cells, they are also found in other cell types." (PMID 37046685, 2023). "Previous studies on tumor therapeutic models reported that administration of tumor antigen (e.g., melanoma-associated antigen recognized by T cells-1 and Wilms’ tumor 1 (WT1))-expressing aAVCs induced potent CD4+ and CD8+ T cell responses." (PMID 36830717, 2023). "The transcription factor encoded by WT1 gene is bidirectional, with the dual function of inhibiting tumor development and activating the transcription of oncogenes." (PMID 38293695, 2023). "Inactivating pathogenic germline variants in WT1, a transcription factor critical for normal renal development that has tumor suppressor function in WT26, were the most common and found in 9/61 (14.8%) patients." (PMID 38110397, 2023). "By regulating endothelial cell proliferation and migration, WT1 has been implicated in tumor angiogenesis." (PMID 36138335, 2023). "In contrast to WT1 variants of purely somatic origin, which are often seen in unilateral WT, all patients with tumor WT1 alterations in the current study were found to have a blood germline variant in WT122." (PMID 38110397, 2023). "We developed an oral vaccine platform using B. longum as an antigen-delivering vehicle to the intestinal immune system and generated a Wilms’ tumor 1 (WT1) oral anticancer vaccine that expresses WT1 protein—a tumor-associated antigen (TAA)." (PMID 35699757, 2023). "This revealed that MECOM, PAX8, SOX17 and WT1 are lineage-enriched, super-enhancer associated master regulators whose cooperative DNA-binding patterns and target genes are re-wired during tumor development." (PMID 37090516, 2023). "Wilms’ tumor gene (Wt1) encodes a transcription factor with zinc finger structure, which plays an important role in tumor formation." (PMID 36829196, 2023). "Instead, peptide vaccines and dendritic cell vaccines have targeted other tumor-associated antigens (TAAs), including WT1, PR3, RHAMM, and MUC1." (PMID 37513844, 2023). "EGFRvIII, CMV pp65, TERT, IDH1, surviving, WT1 have been used as single-antigen peptide and include epitopes of tumor-associated or GBM-specific antigens." (PMID 36874119, 2023).
tumor (continued). "Out of 14 tumor samples from the 9 patients with germline WT1 variants, 10 (71.4%) were found to have acquired tumor somatic activating variants in exon 3 of CTNNB1, which codes for the Wnt pathway effector transcription factor β-Catenin." (PMID 38110397, 2023). "Recent years have seen promising cytotoxic potential from antibodies or T-cell receptors targeting tumor-associated HLA–peptide complexes, such as those involving Wilms tumor protein (WT1)." (PMID 38099269, 2023). "We characterized binding of various WT1-HLA-A*02:01 positive tumor cell lines by all WT1 TED variants." (PMID 38022650, 2023). "CD8+ memory T cells have been elicited in response to tumor antigens such as Wilms’ Tumor 1 (WT1) and melanoma-associated antigen 3 (MAGE-A3) in the MPE." (PMID 36293034, 2022). "On the one hand, WT1 behaves as a classic tumor-suppressor gene, requiring both alleles to be deleted or inactivated for tumor development to occur." (PMID 35453662, 2022). "For example, activation of the proto-oncogenes MYC, ZNF217, and WT1 is associated with DEGs expressed by all three tumor types examined in this study, and therapeutic approaches to inhibition of all three in cancers are being developed." (PMID 36099287, 2022). "We further exploited the possibilities of this PD-1+ 2D3 based T-cell assay, by evaluating the tumor antigen-presenting capacity of PD-L-disrupted IL-15 DCs loaded with mRNA encoding the full-length WT1 protein." (PMID 35250967, 2022). "The multiplex ddPCR assay was developed using tumor cell lines positive for the tumor associated antigens (TAA: WT1, PRAME, BIRC5), with homeostatic ABL1." (PMID 36248870, 2022). "Retrospective analysis of patients with WT and constitutional WT1 pathogenic variant treated at a single centre between 1993 and 2016, reviewing genotype, phenotype, tumour histology, laterality, treatment, patient survival, and kidney outcome." (PMID 34608521, 2022). "In conclusion, our study confirms that WT1 pathogenic variant is associated with early age of WT diagnosis, GU malformation, bilateral tumours, stromal histology, and ILNR." (PMID 34608521, 2022). "Recent advancements in targeted reprogramming [like selective ablation of Wt1 in Ctnnb1 (cadherin-associated protein β1) over-expressing Sc results into Lc cell-like tumor development, manipulation of SF1, GATA4,etc." (PMID 36686449, 2022). "One tumor (M472AAC) carries a deleterious SNV whilst the other three tumors have SVs affecting WT1, often accompanied by loss of expression." (PMID 36230794, 2022). "WT1 encodes a zinc-finger transcription factor that also plays oncogenic or tumor suppressor roles at the transcriptional and post-transcriptional levels in various malignancies." (PMID 35123502, 2022). "No severe adverse events were associated with on-target, off-tumor toxicity in the ten patients treated with autologous WT1-specific TCR-T cells." (PMID 35356211, 2022). "WT1 is a zinc finger transcription factor linked to tumor suppression and oncogenic functions in various brain cancer types." (PMID 36359771, 2022). "Mangiferin exerted its anti-tumor effect through suppressing (Wilms’ tumor 1) WT1-associated with LEF1 in Wnt signaling." (PMID 36080304, 2022). "Even so, WT1 is undeniably a promising tumor-associated antigen, with potentially revolutionary clinical applications (evaluation of prognosis, detection of minimal residual disease/relapse and immunotherapy) which are currently under investigation." (PMID 35453662, 2022). "The Wilms’ tumor suppressor gene, wt1, encodes a zinc finger-containing transcription factor that binds to a GC-rich motif and regulates the transcription of target genes." (PMID 36412640, 2022).